YAP1 (Yes1 associated transcriptional regulator)
Diseases named in the same sentence as YAP1 in open-access papers (continued):
Sharing a sentence is not in itself a finding about the gene and the disease.
ependymoma (continued). "In addition, supratentorial ependymomas most commonly harbored the C11orf95 – RELA fusion (71% of tumors, also known as ZFTA-RELA) and meningiomas most frequently harbored fusions in NF2 and YAP1 (both 15% of tumors)." (PMID 36711972, 2023). "Therefore, we designated nine samples from cluster 1 as RELA+, six samples from cluster 2 as not classified (NC), and one sample as YAP1+ ependymoma." (PMID 34314101, 2021). "We detected nine RELA+, one YAP1+, and four not molecularly classified ependymomas." (PMID 34314101, 2021). "Finally, supratentorial ependymomas harboring neither C11orf95–RELA nor YAP1-MAMLD1 fusions have been reported." (PMID 34008056, 2021). "Interestingly, we found that HOPX was expressed in the three YAP1-MAMLD1-induced human ependymoma, while largely absent in three C11orf95-RELA-induced ependymoma." (PMID 32404936, 2020). "No consensus was made upon morphologically diagnosed ST-ependymomas without RELA/YAP1 fusion." (PMID 27858204, 2017). "In addition, in the ependymal tumor family, the majority of the tumors belong to the supratentorial ependymomas ZFTA fusion-positive containing a C11ORF95-RELA gene fusion, while the remainder harbor fusions involving the YAP1 oncogene (supratentorial ependymomas, YAP1 fusion-positive)." (PMID 37239036, 2023). "Up to 15% of ST ependymoma may not harbor a RELA or YAP1 fusion." (PMID 34885207, 2021). "In the present case, the diagnoses of ependymoma and MN1‐altered astroblastoma were excluded because of the lack of perivascular pseudorosettes and ZFTA, YAP1, and MN1 fusions." (PMID 39492623, 2025). "Herein, we present a detailed series of nine cases of PLAGL1-fused supratentorial tumors, reclassified from a series of supratentorial ependymomas, non-ZFTA/non-YAP1 fusion-positive and subependymomas of the young." (PMID 38581034, 2024). "The current work showed a high proportion (60% of cases) of PLAGL1 alterations discovered in the selected population of supratentorial ependymomas, non-ZFTA/non-YAP1 fused and supratentorial subependymomas of the young." (PMID 38581034, 2024). "To further examine this issue, we studied 18 supratentorial pediatric ependymoma diagnosed between 2003 and 2017 at our institution identified as C11orf95-RELA and YAP1-MAMLD1 fusion-negative." (PMID 33481105, 2021). "Clustering analysis of 16 supratentorial ependymomas revealed 9 tumours with a RELA fusion‐positive signature (RELA+), 1 tumour with a YAP1 fusion‐positive signature (YAP1+), and 6 not‐classified tumours." (PMID 34314101, 2021). "In ST ependymomas with YAP1‐MAMLD1, another molecular subgroup of ST ependymoma, no positivity for L1CAM was observed in any of the 11 cases tested." (PMID 33576087, 2021). "From a clinical perspective, further research is required to assess the impact of ZFTA‐RELA and other fusions on patient survival, as well as the clinical and biological heterogeneity among RELA/YAP1 fusion‐negative and PFA ependymomas." (PMID 34314101, 2021).
liver cancer (73 papers, 2013 to 2025). An epithelial or non-epithelial malignant neoplasm that arises from the liver. "METTL3 governs the m6A modification of Frizzled‐10, increasing its expression in liver cancer stem cells and activating the β‐catenin and yes‐associated protein 1 (YAP1) signaling pathways." (PMID 39802639, 2025). "In liver cancer, the mechanotransducer YAP1 induces target genes associated with epithelial‒mesenchymal transition (EMT) and enhances cancer metastasis." (PMID 40977060, 2025). "We previously showed that actinomycin D represses Yes1 associated transcriptional regulator (YAP1) protein, and its combination with corosolic acid increases its activity against liver cancer." (PMID 37248456, 2023). "Given that YAP1 is closely associated with liver cancer and CSCs, many studies have researched the interaction between LCSCs and YAP1." (PMID 35672802, 2022). "Recent research findings show that YAP1 is correlated with the stemness of liver cancer stem cells, and liver cancer stem cells are closely associated with YAP1-induced tumor initiation and progression." (PMID 35672802, 2022). "Yes-associated protein 1 (YAP1) is a downstream target of the Hippo signaling pathway which promotes the progression of various tumors, including colorectal, bladder, and liver cancers." (PMID 32993038, 2020). "A recent study revealed a unique positive auto‐regulatory feedback loop underlying the interaction between YAP1 and c‐Myc in liver cancer." (PMID 28782275, 2018). "Additionally, dihydroartemisinin was proven to have the ability to reduce the expression of yes-associated protein 1 (YAP1), which has been commonly used as a prognostic marker in liver cancer." (PMID 39202965, 2024). "YAP1-induced liver cancer stemness is also implicated in the TGF-β signaling pathway." (PMID 35672802, 2022). "Beyond its well-characterized functions in liver cancer and lung cancer, YAP1 dysregulation drives pathogenesis in cancers of the breast, gastrointestinal tract, head and neck, and other organs." (PMID 40977060, 2025). "Experimental research has been conducted on the correlation between YAP1 and cisplatin resistance in liver cancer treatment, as well as the issues of nephrotoxicity and weight loss in mice during cisplatin treatment." (PMID 40918140, 2025). "The combined action of inhibiting the cGAS/STING pathway and YAP1 results in a better therapeutic effect on liver cancer." (PMID 40918140, 2025). "On the other hand, when Yap1 was knocked out in liver cancer tissues, PD-L1 was decreased and PD-1 expression was increased." (PMID 40918140, 2025). "Despite this, the significant and robust reduction in HA-tag+ liver cancer specifically in Akt-YAP1 Sox9 iKO livers indicates the context- and oncogenic driver-dependent therapeutic potential of Sox9 elimination in advanced Akt-driven cHCC-CCA tumors." (PMID 39273023, 2024). "Congruently, we found that YAP1 nuclear translocation is compromised in liver cancer tissues of Csn6LKO mice." (PMID 38308184, 2024). "Consistently, the Akt-YAP1 or Akt-NRAS iWT mice developed significant liver cancer, with LW/BW reaching 10 and 12, respectively." (PMID 39273023, 2024). "Recent studies reported MUC13-mediated activation of Wnt/β-catenin signaling in liver cancer, cross-talk of β-catenin, and Hippo-YAP1 signaling pathways in cancer." (PMID 37793774, 2023). "Anti-PD-1 treatment increased YAP1 expression in liver cancer cells and increased the expression of exhausted CD4+ and CD8+ T cells in blood and spleen of liver tumor mice." (PMID 37355637, 2023). "Another study showed that m6A modification of YAP1 affects the translation of YAP1 mRNA and promotes VM formation in liver cancer." (PMID 38012763, 2023). "Recent studies have shown that YAP1 is highly expressed in liver cancer stem cells and its expression was positively correlated with the expression of stemness markers (NANOG, OCT-3/4, and CD133)." (PMID 36045416, 2022).
liver cancer (continued). "The lncRNA MALAT1 regulates the stem cell properties of liver cancer through sponging miR-375 and regulates YAP1 expression, thereby regulating the promotion of liver cancer recurrence and metastasis." (PMID 36052283, 2022). "In particular, we identified that YAP1 expression significantly changed in two large liver cancer cohorts (p = 4.4E-19 and p = 0.030, respectively) [." (PMID 35356283, 2022). "The disturbance of its components caused by pathological conditions will naturally lead to the occurrence of liver cancer and CSCs by affecting YAP1." (PMID 35672802, 2022). "This article reviews the advancements made in research on the mechanisms by which YAP1 promotes liver cancer stem cells and discusses some potential mechanisms that require further study." (PMID 35672802, 2022). "MKLN1-AS positively regulates the expression of YAP1 via targeting and stabilizing YAP1 mRNA, and it enhances the proliferation, migration, and invasion of hepatic cancer cells through YAP1." (PMID 36159561, 2022). "Studies have found that YAP1-TEAD can induce the acquisition of liver cancer stemness, and YAP1-targeting treatment is effective for HCC with a cancer stem cell phenotype." (PMID 35672802, 2022). "The median DFS of patients with the high expression of YAP1 in liver cancer and cholangiocarcinoma is longer, contrary to our results." (PMID 35911146, 2022). "Upregulated circRNA_104075 increased the expression of Yes1 Associated Transcriptional Regulator (YAP1), a target of mir-582-3p, by acting as a sponge of mir-582-3p, ultimately promoting the initiation of liver cancer." (PMID 36249028, 2022). "Reports showed that the YAP1 gene is amplified in tumors such as esophageal squamous cell carcinoma, medulloblastoma, and liver cancer, which promotes tumorigenesis." (PMID 35911146, 2022). "MiR-21-3p-SMAD7/YAP1 axis was identified to better understand the mechanisms of occurrence and development of liver cancer." (PMID 33763375, 2021). "Concurrent nuclear localization of YAP1 and β-Catenin appeared in most liver cancer tissues, suggesting simultaneous activation of these two pathways." (PMID 34395416, 2021). "LncBRM associates with BRM to initiate the BRG1/BRM switch and the BRG1-embedded BAF complex and triggers activation of YAP1 signaling, which maintains the self-renewal of liver cancer stem cells (CSCs) and promotes tumor initiation." (PMID 31582742, 2019). "In the present study, we identified 14 studies that reported the relationship between prognosis of patients with liver cancer and YAP1 overexpression." (PMID 31613226, 2019). "As the determination of cell fate is extremely complicated, a simple inactivation of the Hippo pathway or the over-expression of YAP1 cannot induce liver cancer with an identical histological type." (PMID 28645247, 2017). "Overall, Scrib inhibits liver cancer cell proliferation by suppressing the expression of three oncogenes, Yap1, c-Myc and cyclin D1, thereby functioning as a tumor suppressor in liver cancer." (PMID 28460446, 2017). "Overexpression of LATS1 and the nucleocytoplasmic translocation of YAP1 play an anti-oncogenetic role in the occurrence and development of liver cancer." (PMID 28076850, 2017). "YAP1 up-regulates MALAT1 expression in liver cancer, whereas serine/arginine-rich splicing factor 1 (SRSF1) played an opposing role." (PMID 27835600, 2016). "At present, YWHAZ, JAK2, PDK1 and YAP1 have been identified as cancer relevant direct miR-375 targets in human gastric, esophageal and liver cancer using Luciferase reporter assays." (PMID 24892549, 2014). "When Yap1 was knocked out in liver cancer tissues, the expressions of cGAS and STING decreased." (PMID 40918140, 2025). "However, enolase 1, an RNA-binding protein, binds and stabilizes YAP1 mRNA to promote liver cancer by activating arachidonic acid metabolism in cells." (PMID 40302792, 2025).
liver cancer (continued). "Importantly, some of our observations are similar to those of YAP1 alone-driven liver cancer studies, while a large part of our investigation demonstrates distinct responses, with multiple caveats." (PMID 39273023, 2024). "A recent study led by Dr. Yang’s group demonstrated two dominant roles for SOX9 in YAP1 alone-driven liver cancer: indispensable roles in lineage determinants for HC-to-iCCA formation and responsibility for the severity of YAP1-HCC using AAV8-Cre;Sox9(f/f)-mediated Sox9 ablation." (PMID 39273023, 2024). "Given the widespread expression of SOX9 in fully developed Akt-YAP1 or Akt-NRAS CCA regions as well as poorly differentiated HCC regions, we delivered SB-STOP(flf)−Cas9-sg-Sox9 along with the Akt-YAP1 or Akt-NRAS plasmid into OPN-CreERT2 mice to induce liver cancer." (PMID 39273023, 2024). "However, in contrast to Sox9 LKO or YAP1 alone-mediated liver cancer studies, acute Sox9 disruption using the CRISPR/Cas9 system robustly repressed Akt-YAP1 cHCC-CCA formation, irrespective of tumor fate." (PMID 39273023, 2024). "Therefore, after long-term treatment with sorafenib, liver cancer cells with low YAP1 expression are eliminated, leaving cells with high YAP1 expression, resulting in increased YAP1 expression in sorafenib-resistant HCC cells." (PMID 38967794, 2024). "YAP1 was highly expressed and activated in liver cancer tissues." (PMID 37355637, 2023). "Taken together, these results suggest that HDAC might contribute to the acquisition of liver cancer stemness by increasing the expression and function of YAP1." (PMID 35672802, 2022). "MKLN1-AS could intensify the hyperplasia, migration, and invasion of liver cancer cells by positively regulating YAP1 expression." (PMID 35342418, 2022). "Except for liver cancer, when YAP1 is overexpressed, the median survival time is longer." (PMID 35911146, 2022). "YAP1, as the hub component of Hippo pathway, regulates the progression of liver cancer." (PMID 32169080, 2020). "Combining all these results of other studies and ours, we believe that YAP1 might induce unfavorable prognosis and be an important target in the treatment of liver cancer." (PMID 31613226, 2019). "Moreover, numerous studies have shown higher YAP1 gene expression as well as higher level of YAP1 protein in numerous cancers such as non-small-cell lung, breast, colorectal, and liver cancers." (PMID 29850494, 2018). "In order to demonstrate the involvement of YAP1-TEAD complex in the activation of stem cell markers in liver cancer cells, we evaluated the effect of verteporfin, which was reported to impede the YAP1-TEAD complex formation and does not inhibit, at low doses, basal YAP expression." (PMID 27359056, 2016). "Taken together, our results suggest that the Hippo-YAP1 pathway might be involved in the pathogenesis of liver cancers with stemness, such as EpCAM(+)/K19(+) HCCs and cHC-CCs, which exhibit aggressive biological behavior." (PMID 24086533, 2013). "The mechanism of YAP1 in immune escape of liver cancer remains unclear." (PMID 37355637, 2023). "A previous study had already shown that IQGAP1 may promote liver cancer through YAP1 signalling." (PMID 33672268, 2021). "Moreover, an involvement of IQGAP1 in YAP1-driven oncogenesis was proposed in liver cancer." (PMID 33672268, 2021). "Furthermore, YAP1 is now widely recognized as one of the oncogenic drivers of 11q22 amplification in liver cancer and in many other cancer forms such as ovarian, lung and esophageal squamous cell carcinoma, overexpression of YAP1 is correlated to a worse outcome." (PMID 24559095, 2014). "Western blot assays demonstrated that the total YAP content in primary liver cancer cells (including both HCC and ICC) was significantly higher on the 16 kPa plate, while the p‐S127 YAP1 content was significantly higher on the 2 kPa plate." (PMID 39703167, 2025).
liver cancer (continued). "METTL3 also increases lenvatinib resistance in liver cancer by regulating frizzled class receptor 10 (FZD10) m6A modification, activating the β‐catenin and YAP1 pathways." (PMID 39802639, 2025). "In conclusion, our study provides compelling evidence that targeting YAP1 in combination with DDP can significantly enhance the immune response improve the efficacy of chemotherapy in HCC and enhance CD8+T cells in liver cancer tissues." (PMID 40918140, 2025). "Our findings also confirmed that YAP1 was positively related to cGAS, STING, and GSDMD in liver cancer tissues." (PMID 40918140, 2025). "Previous research has indicated correlation between the expression levels of YAP1 and the infiltration of CD8+ T cells into liver cancer tissues." (PMID 40918140, 2025). "HNF4α directly binds to TEAD4, competing with YAP1 for TEAD4, stalling liver cancer cell proliferation." (PMID 40066231, 2025). "Through bioinformatics analysis, we found that YAP1 was positively related to cGAS and STING in liver cancer (cor/R>0 and P<0.05)." (PMID 40918140, 2025). "In the current study, we mainly used the SB-HDTVI-based Akt-YAP1 and Akt-NRAS HC-derived cHCC-CCA models to investigate the roles of Sox9 in the liver cancer setting, including cHCC-CCA." (PMID 39273023, 2024). "All CWT mice developed a significant burden of liver cancer, with liver LW/BW reaching 30 for Akt-NRAS and 8 for Akt-YAP1 animals, respectively." (PMID 39273023, 2024). "DHA inhibited YAP1 expression and broke immune evasion in liver cancer niche, which was manifested by decreased PD-L1 level and increased CD8+ T cell infiltration in liver cancer cells." (PMID 38155974, 2023). "Impaired degradation of the transcriptional coactivator YAP1 and IL6ST (interleukin 6 cytokine family signal transducer), two proteins deregulated in liver cancer, has been shown to promote tumor growth." (PMID 35435804, 2023). "In liver cancer cells, the bile acid-induced overexpression of IQGAP1 decreased YAP1′s phosphorylation, which inhibits both YAP1-p73 regulated transcription of apoptosis-related genes and pro-growth YAP1-TEAD transcription." (PMID 34439095, 2021). "Targeted validation of screen results evaluated the effects of the RGS-RhoGEFs and Deleted in Liver Cancer (DLC) members on CTGF transcript levels, a common endogenous surrogate for Yap1 activity." (PMID 33504879, 2021). "Given the growing clinical interest in YAP1-targeted therapies, understanding how SALL4 and BMI1 interact within the YAP1 signaling pathway may help refine treatment strategies for aggressive liver cancers." (PMID 40932240, 2025). "YAP1/TAZ regulates amino acid metabolism by upregulating olute carrier family 38 member 1 and SLC7A5, activating mechanistic target of rapamycin complex 1 to spur liver cancer cell proliferation." (PMID 40066231, 2025). "NUAK2 is frequently amplified in breast and liver cancers, where the protein activates YAP1 transcriptional activity via inhibitory phosphorylation of the Hippo pathway kinase, LATS1, which negatively regulates YAP1." (PMID 36975767, 2023). "Moreover, induction of YAP1 by NOTCH can promote the expression of SOX9 and EpCAM stemness markers in liver cancer." (PMID 36045416, 2022). "Volcano map and Boxplots reveal the upregulation of YAP1 in liver cancer cells (adjusted P < 0.001)." (PMID 36401321, 2022). "Yap1 deficiency in liver CSCs can convert them into non-CSCs, and differentiated liver cancer cells became liver CSCs when Yap1 is enforcedly overexpressed." (PMID 30310855, 2018). "When primary liver cancers were divided into two groups according to YAP1 expression, there were 67 cases with YAP1 expression and 85 cases without." (PMID 24086533, 2013). "However, when YAP1 is overexpressed, patients without liver cancer and cholangiocarcinoma have longer median survival time, while those with other types of tumors have a shorter median survival time." (PMID 35911146, 2022).
liver cancer (continued). "Indeed, CCN2 expression was not decreased by YAP1 knockdown but increased by YAP1 overexpression in liver cancer cells, consistent with our results, showing that ATF5 knockdown enhanced the expression of YAP1 and genes upregulated by both stiff ECM and YAP overexpression." (PMID 40124511, 2025). "Interestingly, therapeutic Sox9 iKO significantly decreased Akt-YAP1 tumor burden at 6–8 weeks post-HDTVI, bringing the LW/BW ratios down to 4–5, which is comparable to mice without tumors, suggesting a strong therapeutic effect in Akt-YAP1-driven liver cancer." (PMID 39273023, 2024). "However, several mechanisms of YAP1-induced CSCs have not been demonstrated in liver cancer." (PMID 35672802, 2022). "In hepatocellular-specific Yap1 knockout mice, DDP no longer increased PD-L1 expression or reduced PD-1 expression in liver cancer." (PMID 40918140, 2025). "With Yap1 expression knocked out, DDP no longer increased the expressions of cGAS and STING in liver cancer." (PMID 40918140, 2025).